OLR1 (oxidized low density lipoprotein receptor 1)
Diseases named in the same sentence as OLR1 in open-access papers (continued):
Sharing a sentence is not in itself a finding about the gene and the disease.
bladder cancer (5 papers, 2021 to 2024). "The upregulation of OLR1 expression was positively correlated with clinical stage in certain cancers, such as bladder cancer and clear cell kidney cancer." (PMID 37261073, 2023). "In patients with prostate adenocarcinoma, colorectal adenocarcinoma or bladder cancer, upregulated OLR1 expression was positively correlated with tumour size." (PMID 37261073, 2023). "We investigated the expression levels of 5 model genes (COL5A2, JAG1, MSX1, OLR1, and STC) in normal bladder epithelial cell lines (SV-HUC-1) and bladder cancer cell lines (T24 and 5637)." (PMID 37988196, 2023). "The expression levels of 5 model genes (COL5A2, JAG1, MSX1, OLR1, and STC) were significantly increased in bladder cancer cell lines (T24 and 5637) compared with the normal bladder epithelial cell line SV-HUC-1." (PMID 37988196, 2023). "There is no report on the roles of OLR1, PGF, or SH3BP2 in outcomes of bladder cancer." (PMID 33888644, 2021).
glioblastoma (5 papers, 2020 to 2023). The most malignant astrocytic tumor (WHO grade IV). "In addition to changes in Mmps, we also found that glioblastoma was associated with an increased expression of mRNAs encoding microglial phagocytic receptors—Cd93, Msr1, Cd36, Olr1, Megf10, Clec7a, and Scarf1." (PMID 32299465, 2020).
lipid metabolism disorders (5 papers, 2022 to 2025). "Furthermore, treatment with the antioxidant resveratrol (RSV) and its nanoformulation (RSV-NPs) markedly inhibited tumor growth in mice with lipid metabolic disorders, highlighting their potential to counteract progesterone resistance by disrupting this OLR1/FOXM1/FGF19 axis." (PMID 41270216, 2025).
liver fibrosis (5 papers, 2019 to 2025). "SWT collectively ameliorated liver fibrosis by inhibiting the COL8A1/IL-1β/OLR1 pathways associated with LSEC angiogenesis, adhesion and defenestration, as well as suppressing LSEC secretion of IL-1β to reduce HSC activation." (PMID 39741334, 2024). "Previous researches have suggested that COL8A1, IL-1β and OLR1 were involved in the process of liver fibrosis." (PMID 39741334, 2024). "Overall, our findings suggested that SWT restored liver sinusoidal permeability and alleviated the progression of liver fibrosis by inhibiting COL8A1/IL-1β/OLR1 conducted LSEC angiogenesis, adhesion and defenestration." (PMID 39741334, 2024). "Taken together, these findings suggested that SWT might ameliorate hepatic fibrosis by potentially inhibiting the adhesive process mediated by COL8A1, the angiogenesis process mediated by IL-1β and the LCEC defenestration mediated by OLR1." (PMID 39741334, 2024). "However, the functions of COL8A1 and OLR1 in LSECs during liver fibrosis were not clear." (PMID 39741334, 2024).
lung carcinoma (5 papers, 2021 to 2024). "Here, we found that OLR1 was significantly overexpressed in CAFs of lung cancer and was associated with adverse patient outcomes, and OLR1+ CAFs promote the growth of lung cancer cells in vitro and in vivo, as well as immune evasion." (PMID 39010054, 2024). "Knockdown of PRRX1 significantly inhibited CAFs’ function, while further overexpression of OLR1 restored CAFs’ support for lung cancer cell growth, migration, and immune evasion." (PMID 39010054, 2024). "To elucidate the effect of OLR1+ CAFs on the growth of lung cancer cells, we first knocked down the expression of OLR1 in CAFs and established a co-culture system of BEAS-2B, CAFs, with H1299 or A549 cells." (PMID 39010054, 2024). "PRRX1 promotes OLR1 expression by recruiting H3K27ac and H3K4me3, activating CAFs, and thereby promoting the growth, migration, and immune evasion of lung cancer cells." (PMID 39010054, 2024). "We found that after overexpressing OLR1 in PRRX1low CAFs and co-culturing them with H1299 or A549 cells, the promoting effect on lung cancer cell growth and migration significantly increased." (PMID 39010054, 2024). "Knockdown of OLR1 markedly inhibited CAFs’ support for the growth and immune evasion of lung cancer cells in vitro and in vivo." (PMID 39010054, 2024). "Conversely, reducing OLR1 expression in CAFs weakens these effects, demonstrating the critical role of OLR1 in the supportive function of CAFs for lung cancer progression." (PMID 39010054, 2024). "OLR1 was significantly overexpressed in CAFs and strongly correlated with adverse prognosis in lung cancer patients." (PMID 39010054, 2024). "To further confirm the high expression of OLR1 in lung cancer CAFs, we obtained a single-cell dataset of lung cancer tumors, GSE240001, from the GEO database." (PMID 39010054, 2024). "However, knocking down OLR1 in CAFs attenuates the promoting effect of CAFs on the malignant biological behavior of lung cancer cells." (PMID 39010054, 2024). "LOX1 (OLR1-encoded) is a differentially expressed immunosuppressive phenotype found in low-density neutrophils, and increased tumor infiltration of LOX1+ neutrophils is associated with poor clinical outcomes in colon and lung cancers." (PMID 39261943, 2024). "To further confirm the effect of CAFs and OLR1 on the in vivo growth and metastasis of lung cancer cells, we mixed H1299 cells with BEAS-2B, OLR1high, and OLR1low CAFs in a 1:1 ratio and injected them into C57 mice via the tail vein, followed by anti-PD-1 therapy." (PMID 39010054, 2024). "In the previous experiments, we established that both knocking down OLR1 and PRRX1 can weaken the supportive effect of CAFs on the growth and immune escape of lung cancer cells." (PMID 39010054, 2024). "Therefore, we hypothesized whether PRRX1 could regulate OLR1 expression through transcriptional control and promote CAF activation in lung cancer." (PMID 39010054, 2024).
lupus (4 papers, 2020 to 2024). "The expression of OLR1 (LOX-1 protein gene) significantly decreased in M-MDSCs of Dectin3−/− lupus mice compared with WT lupus mice." (PMID 34480018, 2021).
prostate tumor (4 papers, 2013 to 2017). "In this context, the expression of olr-1 was found to be significantly increased in primary prostate tumors and metastatic prostate tumors compared with normal prostate tissue." (PMID 25170920, 2014).
viral infection (4 papers, 2021 to 2025). "Further studies on the mechanisms of Olr1 induction by a viral infection will provide insights into biological responses to and pathogenesis of infectious diseases far beyond just cytokine induction." (PMID 34344944, 2021). "The expression of Olr1 was increased in the lung by virus infection, with similar induction levels in young and aged hamsters." (PMID 34834944, 2021). "Therefore, cytokine production in viral infection could be activated independently on OLR1." (PMID 34344944, 2021). "Two-way ANOVA demonstrated only effects of virus infection on all cytokines and chemokines (p < 0.0001) but not in the presence or absence of OLR1 (p > 0.05)." (PMID 34344944, 2021). "Markers of polymorphonuclear myeloid-derived suppressor cells (PMN-MDSCs), CEACAM8 (CD66B) and OLR1 (LOX-1), and markers of monocytic MDSCs (M-MDSCs), IL-4R, ITGAM (CD11B), including a functional marker of MDSCs, ARG1, were positively correlated with the severity of viral infection." (PMID 33765435, 2021). "Because inflammation in the lungs and elevated blood cytokine levels in KO mice were similar to those in WT mice after virus infection, OLR1 does not regulate inflammatory responses but is a downstream factor induced by inflammation in the present experimental condition." (PMID 34344944, 2021).
Alzheimer disease (3 papers, 2011 to 2023). A progressive, neurodegenerative disease characterized by loss of function and death of nerve cells in several areas of the brain leading to loss of cognitive function such as memory and language. "Olr1 mutation is a risk factor for Alzheimer’s disease, and its downregulation attenuates brain injury in neonatal hypoxic-ischemic encephalopathy in rats." (PMID 36874245, 2023). "These include various scavenging receptors implicated in Alzheimer’s disease pathogenesis that were increased with age and reversed by microglial repopulation (e.g., A2m, Apoe, Olr1, Sorl1)." (PMID 30477578, 2018).
atrial fibrillation (3 papers, 2020 to 2023). A disorder characterized by an electrocardiographic finding of a supraventricular arrhythmia characterized by the replacement of consistent P waves by rapid oscillations or fibrillatory waves that vary in size, shape and timing and are accompanied by an irregular ventricular response. "Mitochondrial dysfunction is closely related to nuclear factor-κB and oxidized low-density-lipoprotein receptor 1 (OLR1) in atrial tissue during atrial fibrillation." (PMID 35518349, 2022).
breast tumor (3 papers, 2019 to 2021). "In our analysis of the TCGA breast tumor cohort, we observed significant positive correlations between TREM1 expression and the expression of TREM-1 target cytokines (IL1B, IL8, IL6 and CCL2) and markers of MDSCs and TAMs (CD11B/ITGAM, OLR1, CD14 and CD206/MRC1)." (PMID 34956864, 2021).
cervical cancer (3 papers, 2016 to 2021). A primary or metastatic malignant neoplasm involving the cervix. "Through a siRNA-mediate inhibition approach, the depletion of OLR1 suppresses growth of MCF7 (breast cancer), HepG2 (hepatocellular carcinoma) and HeLa (cervical cancer) cells while affecting the growth of non-transformed cell lines." (PMID 28146073, 2017).
hypoxic-ischemic encephalopathy (3 papers, 2023 to 2024). "We confirmed marked lectin-like oxidized low-density lipoprotein receptor-1 (LOX-1) expression in microglial cells in pathological lesions in the neonatal hypoxic-ischemic encephalopathy (nHIE) model brain." (PMID 37268943, 2023).
melanoma (3 papers, 2020 to 2025). A malignant, usually aggressive tumor composed of atypical, neoplastic melanocytes. "Other ARGs, including OLR1, KCNJ8, APP, POSTN, and STC1 showed significant yet heterogenous relationships with immune cells subsets, reinforcing the complexity of immune regulation in melanoma." (PMID 40943183, 2025).
periodontitis (3 papers, 2018 to 2024). An acute or chronic inflammatory process that affects the tissues that surround and support the teeth. "We show that periodontitis cases have lower levels of OLR-1, also denoted lectin-like oxidized low-density-lipoprotein receptor (LOX-1)." (PMID 39101637, 2024). "We present high levels of MMP-12 and low levels of EGF and OLR-1 as interesting candidates that should be further validated in additional cohorts for potential to serve as biomarkers for severe periodontitis." (PMID 39101637, 2024). "The role of EGF and OLR-1 in periodontitis pathogenesis and as possible future biomarkers should be further explored." (PMID 39101637, 2024).
pneumonia (3 papers, 2023 to 2025). An acute, acute and chronic, or chronic inflammation focally or diffusely affecting the lung parenchyma, caused by an infection in one or both of the lungs (by bacteria, viruses, fungi, or mycoplasma.). "OLR1 encodes a low-density lipoprotein receptor (LOX-1) that is associated with vascular injury and inflammatory responses and studies have shown that LOX-1 could attenuate pneumonia-induced lung injury." (PMID 38974914, 2024).
influenza (2 papers, 2021). An acute viral infection of the respiratory tract, occurring in isolated cases, in epidemics, or in pandemics; it is caused by serologically different strains of viruses (influenzaviruses) designated A, B, and C, has a 3-day incubation period, and usually lasts for 3 to 10 days. "Collectively, the results indicated that OLR1 is a critical host factor in intravascular thrombosis as a pathogeny of severe influenza." (PMID 34344944, 2021). "Particularly, thrombin generation from prothrombin in mice with severe influenza was considered critically regulated by OLR1." (PMID 34344944, 2021). "Also, this study shows that OLR1 is critically involved in the first step of thrombus formation by promoting thrombin production in severe influenza." (PMID 34344944, 2021). "Thus, OLR1 is a promising novel therapeutic target to suppress the prothrombotic state during severe influenza." (PMID 34344944, 2021). "Also, this study revealed a significant induction of aortic Olr1 and its critical contribution to the thrombin generation and intravascular thrombosis in the lungs of mice with severe influenza." (PMID 34344944, 2021). "Given its critical role in endotoxin-induced inflammation and endothelial dysfunction, OLR1 was hypothesized to be involved in local and systemic inflammation as well as abnormal blood coagulation observed in mice with severe influenza." (PMID 34344944, 2021). "These previous findings led to the hypothesis that OLR1 is a bridge between inflammation and abnormal blood coagulation and plays an important role in influenza pathogenesis." (PMID 34344944, 2021). "Thus, OLR1 is a promising novel therapeutic target for thrombosis during severe influenza." (PMID 34344944, 2021). "Furthermore, blood coagulation profiles were compared between wild-type (WT) and Olr1 global knockout (KO) mice to investigate the roles of OLR1 as a host factor in cytokine production, coagulation abnormality, and lung intravascular thrombosis during influenza." (PMID 34344944, 2021). "Collectively, these results revealed that OLR1 plays a role in the activation of thrombin generation in severe influenza without affecting the production of inflammatory cytokines." (PMID 34344944, 2021).
morbid obesity (2 papers, 2013 to 2021). An excess of body weight, normally defined as an individual with a body mass index greater than 35 or a body weight greater than one hundred percent of ideal body weight. "In this study we identified that although OLR1 expression levels in ASC is low, morbid obesity and clustering of cardiovascular risk factors significantly increases ASC OLR1 expression." (PMID 24040759, 2013).
prostate adenocarcinoma (2 papers, 2014 to 2022). "Recent studies have indicated that olr1 mRNA is over-expressed in stage III and IV of human prostatic adenocarcinomas." (PMID 25170920, 2014).
sarcoidosis (2 papers, 2020 to 2025). Sarcoidosis is a multisystemic disorder of unknown cause characterized by the formation of immune granulomas in involved organs. "Among the twelve common DEGs, SALL4, WNT10A, RASAL1, CAMK2B were significantly upregulated while GADD45B, KLF4, OLR1, CSF3, WIF1, RAMP3 and AGER downregulated in both sarcoidosis and LC as compared to the controls." (PMID 40797277, 2025).
squamous non-small cell lung cancer (2 papers, 2015 to 2019). "Our previous work illustrated that high expression of OLR1 was associated with short PFS in patients with squamous non-small cell lung cancer, and OLR1 could be applied in constructing a comprehensive predictive model involving patients with squamous NCSLC according to their PFS." (PMID 31718700, 2019).
acne (1 paper, 2025). An inflammatory process of the sebaceous glands which is characterized by comedones, nodules, papules and/or pustules on the skin. "In this study, we investigated the impact of ALA-PDT on lipid metabolism in an acne-like mouse model and in immortalized human sebocytes (XL-i-20), focusing on the role of the OLR1-Wnt/β-catenin pathway." (PMID 39905294, 2025). "This study elucidates a novel mechanistic pathway in ALA-PDT-mediated acne treatment, highlighting OLR1 as a promising target for future therapeutic strategies." (PMID 39905294, 2025). "We speculated that OLR1 was most likely the key gene in acne treatment by ALA-PDT for which has been reported to clear oxidized lipids, whereas the other three genes may promote the secretion of sebum." (PMID 39905294, 2025). "Moreover, investigating the correlation between OLR1 expression levels and acne severity in clinical samples could offer important insights into its potential as a biomarker for ALA-PDT efficacy." (PMID 39905294, 2025). "However, whether the OLR1 and Wnt/β‐catenin pathways are linked to decreased sebum secretion after ALA-PDT for acne vulgaris is unknown." (PMID 39905294, 2025). "This study aimed to elucidate the role of the OLR1-Wnt/β-catenin axis in mediating ALA-PDT-induced lipogenesis inhibition, providing novel insights into its therapeutic mechanism in acne vulgaris." (PMID 39905294, 2025). "IHC staining revealed higher levels of OLR1 expression at the sebaceous gland site than in the untreated group, and both the mRNA and protein levels of OLR1 were elevated by ALA-PDT in the acne-like mouse model." (PMID 39905294, 2025). "By identifying OLR1 as a critical receptor involved in the sebosuppressive effects of ALA-PDT, we propose that OLR1 could serve as a novel therapeutic target for enhancing the efficacy of photodynamic therapy in treating acne vulgaris." (PMID 39905294, 2025).
angiosarcoma (1 paper, 2024). A malignant tumor arising from the endothelial cells of the blood vessels. "Finally, using mIHC staining, we demonstrated that OLR1 + and SPP1 + macrophages were increased in angiosarcoma tissues." (PMID 39658531, 2024).
bladder urothelial carcinoma (1 paper, 2020). "Until now, the roles of PDGFRA, OLR1, RAC3, PDF, OAS1, and SH3BP2 in bladder urothelial carcinoma remain largely unexplored." (PMID 32733809, 2020).
cardiac sarcoma (1 paper, 2024). "Our research also highlights a unique TME in cardiac sarcoma, marked by an increase in myeloid‐derived suppressor cells, specifically SPP1+ and OLR1+ macrophages, which are implicated in advanced tumour progression." (PMID 39658531, 2024).
gallbladder cancer (1 paper, 2024). "Co-culture experiments showed that GBC cells (EH-GB1, GBC-SD, and NOZ) induced higher oxLDL uptake and OLR1 expression in neutrophils compared to HCC cells (Huh7 and MHCC97-H), especially EH-GB1 from metastatic gallbladder cancer." (PMID 38822440, 2024).
glioma (1 paper, 2024). A benign or malignant brain and spinal cord tumor that arises from glial cells (astrocytes, oligodendrocytes, ependymal cells). "For instance, it stabilizes OLR1 mRNA, influencing the OLR1-mediated Wnt/β-Catenin pathway activation, which is linked to TMZ resistance in glioma." (PMID 38474421, 2024).
Hepatic steatosis (1 paper, 2025). Steatosis is a term used to denote lipid accumulation within hepatocytes. "Mechanistically, MCT4 alleviated hepatic steatosis by regulating a group of hub genes such as Arg2, Olr1, Cd74, Mmp8, Irf7, Spp1, and Apoe, which in turn impacted multiple pathways involved in lipid metabolism and inflammatory response, such as PPAR, HIF-1, TNF, IL-17, PI3K-AKT, Wnt, and JAK-STAT." (PMID 40330148, 2025).
Miscarriage (1 paper, 2024). A pregnancy that ends at a stage in which the fetus is incapable of surviving on its own, defined as the spontaneous loss of a fetus before the 22th week of pregnancy. "The GEO database (GSE113790) for recurrent miscarriage and induced miscarriage has documented 15 differential genes related to glycosylation, and existing studies have shown that CD69 and OLR1 are related to RSA." (PMID 39062484, 2024). "The expression of OLR1 in pregnant patients with unexplained recurrent miscarriage was higher than that in non-pregnant uRM patients." (PMID 39062484, 2024).
retinal degeneration (1 paper, 2024). Degeneration of the retina. "Along the same lines, OLR1 is present during AMD and retinal degeneration caused by neovascularization-induced inflammation, and its inhibition may have damage-reductive potential." (PMID 39546296, 2024).
sarcoma (1 paper, 2024). A usually aggressive malignant neoplasm of the soft tissue or bone. "Pseudotime analysis indicated that SPP1+ macrophages were a poor‐differentiated cell subset, while OLR1+macrophages were a high‐differentiation cell subset, which suggesting sarcomas microenvironment also induces matured macrophages phenotype transfer." (PMID 39658531, 2024). "Moreover, we calculated the infiltration scores of exhausted T cells (ex_T), OLR1 + macrophages (OLR1 + MC), and SPP1+macrophages (SPP1 + MC) in sarcomas treated with pazopanib (GSE156344)." (PMID 39658531, 2024).